MIR3682 (microRNA 3682)
Synonyms: hsa-mir-3682; mir-3682
Gene: MicroRNA gene on chromosome 2 (53,849,122 to 53,849,205, reverse strand). Ensembl gene ENSG00000265452.
Homologues: Orthologues: chimpanzee MIR3682 (100% identical).